SMIM31 (small integral membrane protein 31)
Synonyms: h.EPR; LINC01207
Gene: Protein-coding gene on chromosome 4 (164,754,064 to 164,803,795, forward strand). Ensembl gene ENSG00000248771.
Subcellular location: Membrane
Gene Ontology:
Cellular component: membrane
Homologues: Orthologues: chimpanzee SMIM31 (100% identical), macaque SMIM31 (97% identical), pig SMIM31 (76% identical), dog SMIM31 (72% identical), rat Smim31 (66% identical), mouse Smim31 (62% identical).
Diseases named in the same sentence as SMIM31 in open-access papers:
SMIM31 is named in the same sentence as 14 diseases in open-access papers, as found by Europe PMC text mining. Sharing a sentence is not in itself a finding about the gene and the disease. The quoted sentences say what the papers report.
lung adenocarcinoma (4 papers, 2016 to 2020). A carcinoma that arises from the lung and is characterized by the presence of malignant glandular epithelial cells. "SMIM31 has been implicated as a biomarker for survival of colorectal adenocarcinoma and promoting proliferation of lung adenocarcinoma." (PMID 32393195, 2020).
SMIM31 also shares sentences with these, for which no sentence is quoted: tumor (6 papers); cancer (4); colorectal cancer (3); colon cancer (2); colorectal adenocarcinoma (2); gastric cancer (2); colon adenocarcinoma (1); heart failure (1); lung carcinoma (1); non-small cell lung carcinoma (1); pancreatic adenocarcinoma (1); pancreatic cancer (1); pulmonary arterial hypertension (1).